HOPX (HOP homeobox)
Diseases named in the same sentence as HOPX in open-access papers (continued):
Sharing a sentence is not in itself a finding about the gene and the disease.
tumor (40 papers, 2004 to 2025). "HOPX expression is a novel tumor-associated stromal biomarker, it was found to be a potential molecular driver of OC, particularly of the “mesenchymal” OC subtype." (PMID 40002854, 2025). "The EOI residual blast cells depicted overexpression of multiple genes associated with tumor growth and poor outcome including HOPX, SELENOP/SEPP1, and FAM30A/C1orf11053–55." (PMID 37798266, 2023). "On the one hand, HOPX was identified as a tumor suppressor associated with a high degree of promoter methylation leading to epigenetic silencing." (PMID 37344870, 2023). "HOPX also acts as a tumor suppressor, and reduced HOPX expression is associated with several cancers." (PMID 37440461, 2023). "GBM lacks expression of HOPX and its induced expression causes tumor suppressor effect in many GBM cell lines by decreasing survival but proliferation remains unaffected." (PMID 35538578, 2022). "To further disentangle the molecular underpinnings of the tumor-associated stroma/mesenchymal module, we stained tumor sections with antibodies against HOPX." (PMID 27287041, 2016). "Those two results together suggest HOPX is a good candidate driver for the tumor-associated stroma/mesenchymal module, as many of the other genes in module are putative downstream targets of HOPX, either directly or indirectly." (PMID 27287041, 2016). "To examine the potential functional significance of HOPX loss in HNSCCs, we performed gene ontology analysis of genes regulated by HOPX in H376 that were also altered in primary tumours." (PMID 27934959, 2016). "HOPX itself can regulate epigenetics, and defective expression of HOPX can result in loss of tumor suppressive function and differentiation phenotype." (PMID 24287901, 2013). "It is tempting to speculate that genetic characteristics, such as increased tumor mutational burden, might contribute to the tumor-promoting function of HOPX." (PMID 41227363, 2025). "HOPX can influence tissue repair and regeneration, and reduced HOPX expression (through promoter methylation) is associated with several cancers — e.g., colon, breast, thyroid, pancreas — and metastasis risk — e.g., nasopharyngeal — suggesting HOPX acts as a tumor suppressor." (PMID 37440461, 2023). "HOPX (4.26/4.11-fold) is a known colon stem cell marker and is associated with the suppression of tumor metastasis, and TAGLN (2.66/3.73-fold) was found as a novel tumor suppressor and its post-surgical high expression was reported to be associated with good prognosis in stage III CRCs." (PMID 28455965, 2017). "Nonetheless, these results indicate HOPX as a putative novel marker for tumor-associated MSCs." (PMID 27287041, 2016). "To understand how HOPX is associated with the genes in the tumor-associated stroma/mesenchymal module (module 5), we compared these genes with those downregulated in Hopx−/− mice compared to Hopx+/− control mice and found a significant enrichment based on Fisher’s exact test (p = 1.5 × 10−3)." (PMID 27287041, 2016). "Thus, our pan-cancer analysis that highlights HOPX in module 5 led to us to consider HOPX as a potential molecular marker strongly associated with percent stroma and tumor aggression." (PMID 27287041, 2016). "Among them, VIM and HOPX are frequently silenced by promoter hypermethylation in other malignancies, and HOPX functions as a potent tumor suppressor." (PMID 41228323, 2025). "The divergent tumor biological behaviors of HOPX in AML and T-ALL imply the context-dependent function of HOPX in hematologic oncology." (PMID 41227363, 2025). "To understand the mechanisms underlying the altered growth and invasion phenotypes following KO interventions, we performed single-cell profiling of ANXA1-KO, RFX4-KO, and HOPX-KO tumor cells extracted from mouse brains." (PMID 40683881, 2025). "The result showed that the tumor volume and weight were significantly reduced in the HOPX overexpression group compared with the control group." (PMID 40520986, 2025).
tumor (continued). "For example, HOPX, a gene known for its tumor-suppressor functions, including in TC, showed minimal expression in cancer cells of other tumor types, but was highly expressed in papillary TC cells." (PMID 41228323, 2025). "Since HOPX is also expressed in normal brain tissue, the distinction of its expression in the tumor core or border region is more challenging." (PMID 40683881, 2025). "Next, using CRISPR/Cas9 technology to knockout Olig1/2, we found that astrocyte differentiation markers such as GFAP, SOX9, and HOPX were preserved, but tumor cell proliferation was significantly diminished." (PMID 40428395, 2025). "This review describes the identification of HOPX in various tissues and discusses its role in carcinogenesis, as well as its functions in tissue differentiation, lipid metabolism, immunity, and the tumor microenvironment." (PMID 41227363, 2025). "A body of evidence supports the notion that HOPX serves as a tumor suppressor in various types of carcinomas." (PMID 41227363, 2025). "Promoter methylation of at least one HOX related gene (ALX4, CDX2 or HOPX) or ARID1A gene was detected in 83.08% (54/65) of tumor samples." (PMID 40002854, 2025). "Recent studies have found that the HOPX gene functions as a tumor suppressor, and its expression status influences patients’ survival in NSCLC." (PMID 37190150, 2023). "The residual blast cells depicted overexpression of multiple genes associated with tumor growth (SELENOP), metabolism, and stemness (HOPX, FAM30A)." (PMID 37798266, 2023). "Through our literature search, we reviewed the current understandings of HOPX in normal tissues and tumor progression." (PMID 31934721, 2020). "Recently, HOPX suppresses tumor progression through the enhancement of histone H3K9 deacetylation in the snail promoter." (PMID 31934721, 2020). "Accumulating studies proved that HOPX silencing promote primary tumor growth, local invasion, and metastatic colonization." (PMID 31934721, 2020). "With this reasoning we tested HOPX in IHC and showed high level of expression in tumours with YAP1-MAMLD1 fusion." (PMID 32404936, 2020). "In TCGA PTC data set, putative HOPX target co-expressed gene profiles support tumor suppressive function of HOPX." (PMID 31666923, 2019). "Immunohistochemistry confirmed that HOPX protein expression was significantly weak in primary tumor tissues with high Q-MSP values (≥6.1) (p = 0.004)." (PMID 31666923, 2019). "HOPX was discovered as an essential gene for development of the heart, and also functions as a tumor suppressor gene through Wnt inhibition." (PMID 31069006, 2019). "Recent study reported that HOPX suppresses tumor progression by an epigenetic regulation of SNAIL transcription through the enhancement of histone H3K9 deacetylation in the SNAIL promoter." (PMID 31666923, 2019). "In our current study, the hypermethylation of HOPX independently correlated with tumor size among the tumor factors in PTC." (PMID 31666923, 2019). "Compared with the control group, the mice in the HOPX overexpression group had fewer tumour nodes on their lung surfaces." (PMID 28146149, 2017). "In summary, HOPX acts as a tumour suppressor via the epigenetic regulation of SNAIL transcription, which provides a novel prognostic biomarker for NPC metastasis and therapeutic target for NPC treatment." (PMID 28146149, 2017). "Our results demonstrate that HOPX functions as a tumour suppressor in HNSCC and suggest a central role for HOPX in suppressing epithelial carcinogenesis." (PMID 27934959, 2016). "Taken together, our data show that transcriptional regulation by HOPX directly affects tumour cell behaviour and that HOPX functions as a tumour suppressor in HNSCC." (PMID 27934959, 2016).
tumor (continued). "Combining these results with corresponding tumor sections with H&E staining indicate that HOPX and CD73 are uniquely localized to the tumor stroma." (PMID 27287041, 2016). "We have recently identified HOP hoemobox (HOPX) as a tumor suppressor gene candidate, characterized by tumor-specific promoter DNA hypermethylation in human cancers, and it can remarkably inhibit tumors’ aggressive phenotypes." (PMID 22958219, 2012). "HOPX transfectants exhibited G1 arrest with subG1 accumulation, and inhibited tumor forming and invasive ability." (PMID 22958219, 2012). "WB also showed HOPX protein over-expression in tumor tissues as compared to in the corresponding normal tissues." (PMID 22958219, 2012). "We further elucidated that HOPX is a putative tumor suppressor gene critical for tumor aggressiveness in PC." (PMID 22958219, 2012). "Among the identified candidates of TSGs, HOPX is of particular interest in terms of methylation and functional involvement in tumor aggressiveness." (PMID 22958219, 2012). "Unexpectedly, HOPX was increased in expression in tumor tissues, and immunohistochemistry revealed its predominant expression in the Langerhans islet cells, where HOPX was reduced in expression for PC cells with promoter hypermethylation." (PMID 22958219, 2012). "PC tissues had HOPX gene hypermethylation as compared to the corresponding normal pancreas tissues, and its uniqueness was robust to discriminate tumor from normal tissues (AUC = 0.85, P < 0.0001)." (PMID 22958219, 2012). "Indeed, induction of cell cycle arrest and apoptosis is one of the important mechanisms through which HOPX exerts its tumor suppressive function." (PMID 41227363, 2025). "In two tumor suppressor genes RASSF1A and HOPX we observed loss of promoter methylation." (PMID 41280003, 2025). "Recently, it has been reported that HOPX can act as a tumor suppressor and is also able to participate in immune regulation, however, its role and mechanisms in SKCM and its modulation of immune cells remain unclear." (PMID 40520986, 2025). "TC showed high expression of tumor-suppressor genes, including HOPX, in tumor cells." (PMID 41228323, 2025). "The tumor-suppressive function of HOPX can be exerted in different ways." (PMID 41227363, 2025). "Additionally, many studies have revealed that the HOPX gene silencing is significantly related to DNA hypermethylation in cancer, indicating a common epigenetic regulatory mechanism of HOPX in tumor cells." (PMID 41227363, 2025). "The participation of HOPX in carcinogenesis and immunity implies that it may serve as a potential enhancer in tumor immunotherapy." (PMID 41227363, 2025). "Additionally, in patients with renal cell carcinoma showing partial response to immune checkpoint therapy, higher expression of HOPX was detected in CD4+ tumor-infiltrating lymphocytes (TILs) compared to patients with progressive disease." (PMID 41227363, 2025). "We performed an analysis on the phenotypes associated with HOPX expression in SKCM cell lines, and the correlation analysis showed that HOPX expression was negatively correlated with characteristics such as tumor proliferation and positively correlated with inflammation and apoptosis in SKCM cells." (PMID 37344870, 2023). "The TCGA database was used to analyze the expression of HOPX in various normal and tumor tissues." (PMID 37344870, 2023). "Interestingly, tumor drug sensitivity analysis revealed that HOPX also plays an important role in reducing clinical drug resistance." (PMID 37344870, 2023). "Recently, researchers on RNA sequencing analysis have identified that the homeodomain-only protein homeobox (HOPX) gene may act as a tumor suppressor in NSCLC." (PMID 37190150, 2023). "Furthermore, it has been demonstrated that HOPX plays an important role in the Treg-mediated immune tolerance process and that the number of Tregs is significantly increased in tumor patients and correlates with prognosis." (PMID 37344870, 2023).
tumor (continued). "p300, BMP, PAX6 (anti-GBM override), HOPX (tumor suppressive + differentiation), NRSF/REST (astrcytogenic but capable of playing oncogenic role), LIF, and TGF beta: BMP is also involved in the neuronal development but it primarily has far greater gliogenic role." (PMID 35538578, 2022). "HOPX is primarily astrocytogenic and also works as tumor suppressor in a time-dependent manner." (PMID 35538578, 2022). "c-Fos is induced by 17β-estradiol (E2) via a SRE-dependent manner in human uterine endometrial cancer (HEC) or breast cancer cell lines, while HOPX could act as a tumor suppressor by regulating the SRF-c-fos-cyclin D1 pathway in HEC." (PMID 31934721, 2020). "HOPX co-localised with cells expressing nuclear YAP1 in LATS1/2 cKO tumours." (PMID 32404936, 2020). "HOPX plays a critical role in epithelial cell homeostasis and serves as a tumor suppressor in head and neck cancer (HNSCC), which is markedly down-regulated in three different subtypes of HNSCC, including tumors of the oral cavity (OSCC), oropharynx (OPSCC), and nasopharynx (NPC)." (PMID 31934721, 2020). "Based on these proteins interacting with HOPX, we could do more to study the relevant anti-tumor molecular signaling pathways of HOPX." (PMID 31934721, 2020). "HOPX is involved in multiple organ development and acts as a tumor suppressor in various cancers." (PMID 31666923, 2019). "We revealed that HOPX plays suppressive roles in tumor angiogenesis, proliferation, or invasion." (PMID 31666923, 2019). "Moreover, enforced HOPX expression inhibited tumor progression, and knockdown of endogenous HOPX restored the tumor aggressiveness by influencing several mechanism of cancer cell activities." (PMID 31666923, 2019). "Correlation of HOPX Q-MSP value with each clinicopathological tumor factor was analyzed." (PMID 31666923, 2019). "Moreover, H&E staining confirmed that the HOPX overexpression group had smaller and fewer microscopic tumour nodules." (PMID 28146149, 2017). "Moreover, the inguinal lymph nodes in the HOPX overexpression group had smaller volumes and fewer pan-cytokeratin-positive tumour cells than those in the vector group." (PMID 28146149, 2017). "Haematoxylin and eosin (H&E) staining of the primary tumours showed that tumours in the HOPX overexpression group exhibited sharp edges that expanded as spheroids, indicating a less aggressive phenotype with invasion towards the skin, muscle and lymphatic vessel than the vector group." (PMID 28146149, 2017). "Therefore, we conclude that HOPX acts as a tumour suppressor mainly with regard to NPC metastasis and chemosensitivity." (PMID 28146149, 2017). "However, in the DDP-treatment group, the tumour volumes and weights were significantly suppressed following HOPX overexpression." (PMID 28146149, 2017). "Interestingly, HOPX expression was more than 100% higher in each of the remaining three tumours compared to matched normal controls." (PMID 27934959, 2016). "Of the 20 cases for which methylation and expression were available for both the tumour and matched normal tissues, HOPX was lower in 17 (85%) of cases; 3 of the 17 tumours showed evidence of HOPX-β promoter hyper-methylation and this was associated with a significant reduction of expression." (PMID 27934959, 2016). "HOPX has been demonstrated to have tumor suppressor function in various cancers, including CRC." (PMID 24287901, 2013). "Hence, our conclusion on tumor suppressive role of HOPX on PC was based largely on epigenetic characteristics in primary PC, and results of PC cell lines remained supplementary." (PMID 22958219, 2012). "More importantly, HOPX could inhibit tumor-forming ability in soft agar, which is supposed to represent metastatic trait of tumor cells." (PMID 22958219, 2012). "HOPX actually suppressed tumor aggressiveness of PC cells (PANC-1 and MIA Paca2)." (PMID 22958219, 2012). "Also, enforced HOPX expression inhibited tumor growth and RNA interference knockdown of endogenous HOPX restored it." (PMID 22958219, 2012).
tumor (continued). "In summary, our study suggests that HOPX can be used as a diagnostic and prognostic marker in SKCM patients and that it may participate in tumor immunotherapy by modulating the biological activity of various immune cells and attenuating clinical drug resistance in patients." (PMID 37344870, 2023). "In addition, a lung colonization model was used to determine whether HOPX restoration affected NPC tumour progression in vivo." (PMID 28146149, 2017). "In contrast, in a recent report depicting six master regulators (AEBP1, HOPX, PRRX1, SNAI2, ZEB1, ZEB2) of the TCGA “mesenchymal” subtype, they employed a network-based strategy to uncover the molecular mechanism underlying the discrete mesenchymal subtype in whole tumor tissues of serous OC." (PMID 27081703, 2016). "In the diffusely growing U3180MG xenografts, targeting of either HOPX or RFX4 prolonged survival, decreased tumor cell density, and (in the case of RFX4) led to altered morphology of the tumor cells." (PMID 40683881, 2025). "Genes associated with proliferation such as proliferating cell nuclear antigen (PCNA), prominin 1 (PROM1), HOP homeobox (HOPX), and olfactomedin 4 (OLFM4) were also upregulated in LPS treated IBD intestinal organoids and tumor enteroids." (PMID 35884586, 2022). "Differential analysis showed that proliferation and antigen presentation genes, such as STMN1 and HLA‐DRA, were slightly up‐regulated in tumour cells, whereas differentiation molecules, such as KRT13, HOPX and CD24, were highly expressed in normal cells." (PMID 35608199, 2022). "The overexpression of HOPX, upregulation of p21, and downregulation of cyclin D1 and CDK4 regulate the progress of migration and invasion of MDA-MB-468 cells to modulate tumor growth of the breast." (PMID 34235216, 2021). "Seven genes (CACNB2, IL34, CGNL1, CNTN3, GAS7, HOPX, and PBX1) regulated by miR-31-5p and miR-31-3p were identified as putative tumor suppressors." (PMID 34201353, 2021). "Among the 4 genes, ALDH1L1 and HOPX exhibited decreased inter-tumor variance of methylation levels after NAC treatment; meanwhile, WNT5A and SOX9 showed increased inter-tumor variance." (PMID 30774927, 2019). "A tumour metastasis PCR array showed that the expressions of many genes (ECADHERIN, NME4, SYK, CD44 and IL1B) were changed in NPC cells with HOPX overexpression." (PMID 28146149, 2017). "We show that HOPX mRNA levels are reduced in OSCC and NPC cell lines and tissues and there is a general reduction of HOPX protein expression in these tumours and OPSCCs." (PMID 27934959, 2016). "In the patients with poor tumor resectability and prognosis, CD73 and HOPX expression is riddled throughout the tumor tissue." (PMID 27287041, 2016). "Cell cycle analysis further revealed that HOPX increased fractions of both subG1 fraction and G0/G1, accompanied by decreased fraction of both S and G2/M, indicating that both G1 arrest and apoptotic sensitivity may be at least partially involved in tumor suppressive traits of HOPX-expressing cell." (PMID 22958219, 2012). "The analysis of Olig1/2F/+; ISF/+ tumor-bearing mice at P40 demonstrated significantly reduced tumor sizes compared to controls, while tumor cells maintained high expression of astrocytic markers GFAP and HOPX." (PMID 40428395, 2025). "The KO of HOPX in U3180MG increased median survival (p-value = 0.0002) and these tumors appeared less aggressive than the control, as judged by reduction of tumor density." (PMID 40683881, 2025). "Other intestinal stem cell markers and genes associated with proliferation, notably proliferating cell nuclear antigen (PCNA), prominin 1 (PROM1), HOP homeobox (HOPX), and olfactomedin 4 (OLFM4), were also increased in LPS-treated IBD intestinal organoids and tumor enteroids." (PMID 35884586, 2022). "HOPX had also been shown to have tumor suppressor functions in various cancers including CRC, and HOPX might be involved in inhibiting CRC metastasis." (PMID 36293319, 2022).